CD99 (CD99 molecule (Xg blood group))
Diseases named in the same sentence as CD99 in open-access papers (continued):
Sharing a sentence is not in itself a finding about the gene and the disease.
Ewing sarcoma (continued). "When diagnosing Ewing sarcoma of the lung, the central role lies in distinguishing the histological findings of ES from its mimics, as well as identifying essential IHC markers such as CD99, FLI1, and NKX2.2." (PMID 41278275, 2025). "However, a similar anti‐CD99 IHC membrane structure has been found in Ewing sarcoma." (PMID 39229296, 2024). "The opposing activities of Src detected in the osteosarcoma study and the present study may reflect the different sarcoma types or different experimental conditions employed (CD99 exogenous expression in osteosarcoma versus endogenous GDF6 silencing in Ewing sarcoma)." (PMID 33147457, 2020). "In this way, Baldauf and coworkers proposed a model of workflow to establish a diagnosis of ES: in the case of clinically and/or radiologically suspected Ewing sarcoma, a biopsy should first be stained for CD99." (PMID 32675940, 2020). "In addition, although the molecular mechanism is not well understood, there is evidence that CD99 contributes to Ewing sarcoma growth: CD99 knockdown in Ewing sarcoma cells inhibited anchorage-dependent and anchorage-independent growth, and reduced tumorigenicity." (PMID 33147457, 2020). "Thus, CD99 alone is unreliable to definitively diagnose Ewing sarcoma." (PMID 29416716, 2018). "However, additional positive immunostaining for CD99 was strongly suggestive of Ewing’s sarcoma." (PMID 26549660, 2015). "In summary, the CD99-targeted NV103 platform demonstrated significant potential to improve both the efficacy and tolerability of chemotherapy in Ewing sarcoma." (PMID 41542564, 2026). "Imaging revealed a retroperitoneal, necrotic mass and biopsy with immunohistochemistry confirmed retroperitoneal Ewing sarcoma with NKX2.2 and CD99 positivity." (PMID 40255709, 2025). "A more recent surfaceome analyses revealed many new Ewing sarcoma cell surface targets including ENPP1 and CDH11 in addition to known IL1RAP, STEAP1, ADGRG2 and CD99, providing newer cell surface targets for immunotherapeutic application in Ewing sarcoma." (PMID 40442778, 2025). "CD99 positivity is seen in both MC and Ewing’s sarcoma, along with vimentin, CK, NKX2.2, FLI1, and CD99." (PMID 40585664, 2025). "Growth and differentiation factor 6 (GDF6) in Ewing sarcoma, paired immunoglobulin-like type 2 receptors (PILRs), CD99 antigen-like protein 2 (CD99L2), and CD99 itself were shown to act as ligands of CD99 and contribute to the regulation of the immune system." (PMID 41514929, 2025). "The consistent high-level expression of CD99, coupled with an EWS gene rearrangement involving FLI1, ERG, or, in rare cases, other ETS genes, serves as hallmarks of Ewing sarcoma." (PMID 40427525, 2025). "CD99, a commonly used marker in the diagnosis of round cell tumors, shows weak and patchy staining in BCOR-CCNB3 sarcomas, distinguishing it from Ewing sarcoma, where it exhibits strong, diffuse membranous positivity." (PMID 40932977, 2025). "Case presentation: 36-year-old man with rectosigmoid mass showing small round blue cells with pseudorosettes, CD99 and FLI1 positive, diagnosed as Ewing sarcoma; managed with surgical resection followed by chemotherapy." (PMID 41458270, 2025). "IHC revealed intense positivity for Ki-67 (70%), CD99, vimentin, and FLI-1, establishing the diagnosis of extraosseous Ewing's sarcoma." (PMID 40896068, 2025). "These uniform, small, round cells that stain positive for CD99 (i.e., the product of MIC-2 genes) are the typical and classical microscopic description for Ewing sarcoma, as they are found in more than 90% of cases." (PMID 39588414, 2024). "Acute lymphoblastic lymphoma/leukemia resembles Ewing sarcoma in terms of morphology and clinical characteristics, especially in cases that are CD45-negative and CD99-positive." (PMID 38280044, 2024).
Ewing sarcoma (continued). "The immunohistochemical profile closely matched that of the initial tumor; however, positive staining for CD99 and confirmation of the EWSR1 gene translocation through fluorescent in-situ hybridization (FISH) supported a diagnosis of Ewing sarcoma." (PMID 39439958, 2024). "In Ewing sarcoma patients, CTC characterization using tumor-specific markers (i.e., CD99 expression) and chromosomal translocations (e.g., EWSR1-FLI1 transcript fusion gene amplification) has been described." (PMID 38392061, 2024). "Ewing sarcoma displayed the anticipated homogenous cell population, strong NKX2.2 expression, and CD99 positivity across various sites." (PMID 38234938, 2023). "Remarkably, the overexpression of CD99 in the peripheral blood, together with the low levels of CD45 (CD99+CD45−), has been related to a very poor prognosis in children experiencing Ewing’s sarcoma." (PMID 37298173, 2023). "PNET/Ewing sarcoma family exhibit common histology phenotype, expression of MIC-2 protein (CD99), CD56, and neuron-specific enolase." (PMID 35633271, 2022). "Since a differential diagnosis of Ewing's sarcoma is difficult, the EWSR1 rearrangement combined with CD99 immunostaining allowed us to give an exact classification for each patient and differentiated between the different entities." (PMID 36164527, 2022). "A study on a large cohort of Moroccan patients with Ewing's sarcoma showed that the combination of EWSR1 rearrangement and CD99 immunostaining is more sensitive and specific than each test alone." (PMID 36164527, 2022). "We then used ligand-binding assays to test the role of CD99 and CD99L2 as the GDF6 prodomain receptor in Ewing sarcoma." (PMID 33147457, 2020). "Ewing sarcoma (ES) is the prototype for an undifferentiated sarcoma with such a phenotype, although it is shared by several other sarcoma entities together with the membrane expression of CD99." (PMID 32155762, 2020). "This suggests that endogenous GDF6 stimulates the interaction between CD99 and CSK in Ewing sarcoma." (PMID 33147457, 2020). "GDF6 pro-FLAG bound to control siRNA-transfected A673 cells, and this binding was significantly reduced by silencing of CD99 and/or CD99L2, indicating that the GDF6 prodomain binds CD99/CD99L2 in Ewing sarcoma." (PMID 33147457, 2020). "In particular, the high expression of the chosen markers was highly effective in discriminating Ewing sarcoma from EWSR1-ETS-negative Ewing-like sarcomas, which expressed CD99 at high levels in 88% of our cases." (PMID 29416716, 2018). "Therefore diagnosis of Ewing sarcoma, pPNET or PNET (NOS), should be based on analysis of EWSR1 gene rearrangement or immunohistochemical analysis of FLI-1 not only on histological findings, associated with a limited immunophenotype usually represented by expression of CD99." (PMID 25960901, 2015). "Positivity for LCA in lymphoma, CD99 immunoreactivity and EWS/Fli1 translocation in extraskeletal Ewing sarcoma." (PMID 25253623, 2014). "CD99, the MIC2 gene product best known for its presence in Ewing’s sarcoma and primitive neuroectodermal tumors, is another marker that is expressed by sex cord-stromal tumors; furthermore, the CD99 antibody reacts with normal granulosa and Sertoli’s cells." (PMID 25120684, 2014). "This study supports the role of CD99/MIC2 as differentiation antigen of osteoblasts and a Ewing’s sarcoma cell line with neuroectodermal phenotype." (PMID 29147265, 2011). "Schultze-Mosgau noted that CD99 expression in Ewing sarcoma is not entirely unique, but CD99 testing remains mandatory because 95% of ES cases are positive for this marker." (PMID 40060231, 2025). "For Ewing sarcoma, CD99 expression is sensitive but not specific and must be interpreted alongside FLI1, which improves specificity." (PMID 41458270, 2025). "The most specific immunohistological marker used in diagnosing retroperitoneal Ewing sarcoma is NKX2.2, while CD99 and FLI1 may serve as supporting markers in confirming the diagnosis." (PMID 40255709, 2025).
Ewing sarcoma (continued). "GDF6 has also been reported to bind to CD99 and to regulate Src signaling in Ewing sarcoma, although it is not expressed in immune cells." (PMID 41514929, 2025). "Furthermore, biomarkers such as TTF-1 and CDX-2 can be used to identify metastatic MCC, whereas LCA, CD99, S100, HMB-45, and SOX-10 can exclude lymphoma, Ewing sarcoma, and malignant melanoma." (PMID 41245381, 2025). "CD99 has also been found to be upregulated in various cancers such as AML and Ewing sarcoma." (PMID 39007347, 2024). "These tumors do not show the homogeneous membranous CD99 expression, and they lack the stereotypical cytology of classical Ewing sarcomas." (PMID 39031200, 2024). "In this study, we discovered a high-affinity human anti-CD99 antibody, NOA2, capable of binding Ewing sarcoma cells, and subsequently explored the in vitro and in vivo activity of this antibody to engage macrophages, impact tumor growth, and modulate macrophage function." (PMID 38534214, 2024). "In particular, high-grade endometrial stromal sarcomas have round blue cell morphology, may have pseudo rosettes and are commonly positive for CD99, Cyclin D1 and KIT, all of which are also positive in Ewing sarcoma." (PMID 39777304, 2024). "Histologically, the tumors consist of generally uniform round cells with vesicular nuclei of finely dispersed chromatin and hyaline cytoplasm.More than 95% of tumors express the cell surface protein CD99 (also named MIC2), which has been used as a marker for Ewing sarcoma." (PMID 36672331, 2023). "These included olfactory neuroblastoma (excluded based on clinical absence of nasal involvement) and Ewing sarcoma (due to lack of membranous CD99 staining and a negative EWSR1 FISH test)." (PMID 38031161, 2023). "The absence of GFAP, the high proliferation index and the CD99 positivity in particular led to the exploration of further potential differential diagnoses, e.g. a metastasis of a neuroendocrine carcinoma or a Ewing sarcoma." (PMID 36414742, 2022). "Immunohistochemistry revealed membranous positivity for CD99, diffuse nuclear positivity for NKX2.2, diffuse cytoplasmic positivity for vimentin and sporadic positivity for Syn and EMA, strongly suggesting a diagnosis of Ewing’s sarcoma." (PMID 36046048, 2022). "Staining for CD99 and PAS are widely used for Ewing sarcoma diagnosis in patients." (PMID 35285802, 2022). "Ewing sarcomas/PNETs show CD99-positive staining in the cytoplasm and not in the cell membrane and are negative for CK, EMA, WT1, and desmin." (PMID 34193155, 2021). "Ewing sarcoma tumors do not exhibit squamous differentiation, with diffuse positive CD99 IHC staining and negative CK and NUT staining." (PMID 32149149, 2020). "Notably, the same outcome was obtained by exposing Ewing sarcoma cells to exosomes derived from cells deprived of CD99, confirming the sequential path of miR34a/Notch/NF-κB and MAPK upregulation that follows CD99 silencing." (PMID 29534016, 2018). "The introduction of EWS-FLI1 into neuroblastoma, rhabdomyosarcoma, or mesenchymal stem cells turned on CD99 expression while the silencing of EWS-FLI1 in Ewing sarcoma cells does not affect high-level CD99 expression." (PMID 29534016, 2018). "CD99 expression was not very specific for Ewing sarcoma compared to other sarcoma entities as well as Ewing-like sarcomas." (PMID 29416716, 2018). "CD99 is not specific for Ewing sarcoma and can be positive in other cancers such as poorly differentiated synovial sarcomas, small round cell osteosarcomas, rhabdomyosarcomas, gliomas, and granulosa cell tumors." (PMID 30319719, 2018). "Next, expression levels of eight EWS-FLI1 associated target genes (GLI1, NEX2.2, CyclinD, c-MYC, NR01B, IGF1R, EZH2, and CD99) which were known to be upregulated, and three genes (FOXO1, IGFBP3, and LOX) known to be down regulated in Ewing’s sarcoma was assessed." (PMID 28775288, 2017).
Ewing sarcoma (continued). "Diagnosis of Ewing sarcoma should be based on positive immunohistochemical reactions for vimentin (+++) and CD99 (+++) and negative reaction for desmin, actin, ML, and CD10, associated as in our experience with a high (90%) proliferative index Ki67." (PMID 25960901, 2015). "Diffuse membranous positivity for CD99 led to a diagnosis of Ewing’s sarcoma/PNET and ruled out small cell carcinoma." (PMID 26549660, 2015). "Fibroblasts isolated from Ewing's sarcomas and bone stromal cells consisted almost entirely of spindle-shaped mononuclear cells, which did not stain immunohistochemically for CD99, CD14 or CD68 or VNR and TRAP." (PMID 17533390, 2007). "On the one hand, CD99 negativity is not typical for Ewing sarcoma." (PMID 40565358, 2025). "CD99 is identified in approximately all tumors in the Ewing sarcoma family and, despite not being the most specific, its positivity may contribute to the establishment of the differential diagnosis among small round-cell tumors." (PMID 38223368, 2024). "Thus, the use of CD99 expression by tumor cells is not sufficient to make the diagnosis of Ewing sarcoma." (PMID 38459600, 2024). "CD99 and NKX2.2 positivity gave rise to the thought that it could be the Ewing sarcoma." (PMID 36765856, 2023). "The presence of undifferentiated small round cells, positive for CD99 immunohistochemistry in a membranous pattern, and also positive for NKX2.2 in a nuclear pattern may represent a pitfall since Ewing sarcoma (EWS), another relatively frequent primary bone tumor, is also positive for these markers." (PMID 34132499, 2022). "The presence of CD99+CD45− mononuclear cells in the bone marrow from patients without Ewing sarcoma at a higher rate compared to PBMCs, representing early monocytic progenitor cells, demonstrate at present no sufficient specificity of BM testing for Ewing sarcoma diagnosis." (PMID 34063272, 2021). "The consistent, high-level expression of CD99 and the presence of a EWS gene-rearrangement with FLI1, ERG or, in rare cases, other ETS genes are the hallmarks of Ewing sarcoma, and a functional relation exists between the two, although that relation remains unclear." (PMID 29534016, 2018). "Since non-monocytic MSs are mostly CD99-positive, other blue round cell tumors of the pediatric age such as Ewing sarcoma/PNET or medulloblastoma may mimic MS." (PMID 25805673, 2015). "Also it should be remembered that CD99 positivity in synovial sarcomas does not feature the typical crisp membrane staining most often observed in Ewing’s sarcoma." (PMID 25699170, 2015). "In fact, membranous expression of CD99 is sensitive but not specific for Ewing sarcoma since it can be found in lymphoblastic lymphoma, alveolar rhabdomyosarcoma, synovial sarcoma, some carcinomas (including endometrioid and serous adenocarcinoma), and many others." (PMID 25960901, 2015). "Although not specific for PNET or Ewing sarcoma, CD99 is generally present in these tumors." (PMID 23762725, 2013). "However, silencing EWS-FLI1 in Ewing sarcoma cells does not affect high-level CD99 expression." (PMID 40427525, 2025). "Moreover, tumour morphology, Ki-67 proliferative index (Fig. EV4D,E) and tumour immunohistochemical staining for PHOX2B (neuroblastoma) and CD99 (Ewing sarcoma) remained unchanged between tumours generated from non-bioprinted and bioprinted cells (Fig. 5Bii,Cii)." (PMID 41034452, 2025). "However, because of the retroperitoneal involvement, rosette formation by morphology and diffuse staining for CD99, Ewing sarcoma could not be excluded." (PMID 39777304, 2024). "Cluster of differentiation 99 (CD99) and Friend leukemia integration 1 (FLI-1) are currently accepted for the diagnosis of Ewing Sarcoma but they can also be expressed in a wide range of cancer entities different from ES." (PMID 36776337, 2023). "However, negative CD99 immunogenicity strongly argues against the diagnosis of Ewing sarcoma." (PMID 36672331, 2023).
Ewing sarcoma (continued). "Ewing sarcoma cells lacking CD99 but expressing EWS-FLI1 show significantly inhibited growth, migration, and metastasis, suggesting that CD99 expression is vital for malignancy." (PMID 40427525, 2025). "As both CD99 and EWSR1-WT-1 fusion genes were negative, the diagnoses of desmoplastic small round-cell tumor and Ewing sarcoma were excluded." (PMID 39055564, 2024). "Surprisingly, we found that Ewing sarcoma depends on the prodomain, not the BMP domain, of GDF6, and demonstrated that the GDF6 prodomain uses CD99 as a cell surface receptor to inhibit Src." (PMID 33147457, 2020). "In a patient with atypical morphology or CD99 negative Ewing sarcoma, almost all respondents (97%) felt that FISH was necessary to confirm the diagnoses of Ewing sarcoma." (PMID 33488267, 2020). "The Ewing's sarcoma (EWS) tumor marker CD99 was found to be overexpressed in the vasculature of different solid tumor types, but CD99 was not expressed in normal healthy tissues." (PMID 31001265, 2019). "Atypical teratoid/rhabdoid tumor (AT/RT) and Ewing sarcoma (EWS) was excluded based on maintained INI1 expression and absence of the EWS/FLI1 translocation and CD99 expression." (PMID 26883117, 2016). "Additionally, negative staining for NKX2.2, CD99, desmin, S100, SOX10, HMB45, GATA3, CD45 (LCA), CD3, and CD20 further excluded diagnoses of Ewing sarcoma, rhabdomyosarcoma, melanoma, and the majority of non-Hodgkin lymphomas." (PMID 39404971, 2024). "Remarkably CD99 antigen is found also in SS and epithelial markers may be absent in PDSS and focally present in Ewing Sarcoma/PNET." (PMID 25699170, 2015).